TBL1XR1 (TBL1X/Y related 1)
Diseases named in the same sentence as TBL1XR1 in open-access papers (continued):
Sharing a sentence is not in itself a finding about the gene and the disease.
developmental delay (8 papers, 2016 to 2025). "The child’s genotype was consistent with the clinical phenotype, and the final diagnosis of West syndrome and global developmental delay caused by a heterozygous mutation in TBL1XR1 was confirmed." (PMID 37171308, 2023). "It was determined that a heterozygous mutation in the TBL1XR1 gene caused West syndrome and global developmental delay." (PMID 37171308, 2023). "We report the case of a child with West syndrome and a global developmental delay caused by a heterozygous mutation in the TBL1XR1 gene." (PMID 37171308, 2023). "We reviewed all published cases and summarized the clinical features and genetic variants of TBL1XR1, and found that all cases had developmental delay." (PMID 35611576, 2022). "309Kb and 521Kb microduplications of TBL1XR1 leads to developmental delay, intellectual disability, ASD, and hearing loss." (PMID 32449767, 2020). "Children with likely pathogenic mutations in TBL1XR1 have developmental delay often with autistic features." (PMID 26740553, 2016). "Furthermore, TBL1XR1 variants have been implicated in various neurodevelopmental disorders (NDDs), including developmental delay (DD), intellectual disability (ID), and autism spectrum disorder (ASD), which frequently co-occur." (PMID 41444645, 2025). "TBL1XR1-related disorder encompasses a spectrum of clinical presentations, marked by early developmental delay ranging in severity, with a subset of patients experiencing developmental regression towards the second decade." (PMID 38378692, 2024). "While developmental delay is nearly universal in TBL1XR1-related disorder, regression occurs in one-third only and most commonly affects language function." (PMID 38378692, 2024). "TBL1XR1-related disorder encompasses a spectrum of clinical presentations, marked by early developmental delay ranging in severity, with a subset of patients experiencing developmental regression in later childhood." (PMID 38378692, 2024). "TBL1XR1 mutations have been associated with neurological disorders presenting variegated manifestations that may include brain malformations, social difficulties, intellectual disability, developmental delay, learning disability, hearing loss, schizophrenia, and seizures." (PMID 33708771, 2021). "Many of the early presenting signs and symptoms reported by caregivers were nonspecific, such as developmental delay, hypotonia, and growth issues, highlighting the importance of inclusion of TBL1XR1 on gene panels." (PMID 38378692, 2024).
autism spectrum disorder (6 papers, 2016 to 2025). A spectrum of developmental disorders that includes autism, and Asperger syndrome. "Mutations in and abnormal expressions of TBL1XR1 have been associated with autism spectrum disorders, intellectual disability and some cancers." (PMID 41012410, 2025). "As an example, identification of de novo mutations in patients linked the FMRP partner candidates Tbl1xr1 and Chd4 to autism spectrum disorders." (PMID 36237573, 2022).
cervical cancer (6 papers, 2015 to 2024). A primary or metastatic malignant neoplasm involving the cervix. "By controlling the expression of Snail and Twist, TBL1XR1 could influence EMT to cause cervical cancer cells to metastasize via the Wnt/-catenin pathways." (PMID 38347836, 2024). "Another study in cervical cancer revealed that TBL1XR1 directly bound to the snail promoter and the Twist promoter." (PMID 38347836, 2024). "TBL1XR1 mRNA and lncRNA799 expression was found to be significantly correlated in each cervical cancer tissue sample (r2 = 0.160; p < 0.001)." (PMID 30439646, 2018). "Western blot analysis demonstrated that lncRNA799 promotes the expression of transducing β-like protein 1-related protein (TBL1XR1), and that lncRNA799 and TBL1XR1 expression show strong correlation in cervical cancer." (PMID 30439646, 2018). "In the present study, lncRNA799 overexpression resulted in a significant increase in TBL1XR1 expression and increase in cervical cancer metastasis, whereas lncRNA799 knockdown had the opposite effect." (PMID 30439646, 2018). "It was reported that TBL1XR1 promoted cervical cancer cell metastasis by NF-kB and Wnt/β-catenin pathways to induce epithelial-to-mesenchymal transition (EMT)." (PMID 27672238, 2016). "Moreover, TBL1XR1 was identified as an independent prognostic marker for the outcome of cervical cancer patients." (PMID 38347836, 2024). "In addition, lncRNA799 promoted metastasis of cervical cancer via altering the production of TBL1XR1 by functioning as a relatively competitive endogenous RNA (ceRNA) for miR-454-3P." (PMID 38347836, 2024). "Thus, TBL1XR1 induced cervical cancer cells EMT partially by regulating the NF-κB pathway." (PMID 38347836, 2024). "Thus, the TBL1XR1 protein could be a marker of cervical cancer prognosis and play a key role in cervical cancer invasion and metastasis." (PMID 30439646, 2018).
Intellectual disability (6 papers, 2016 to 2025). "TBL1XR1 is part of the NCoR/SMRT complex, which regulates Wnt/β-catenin signaling by modulating transcriptional repression, and mutations in TBL1XR1 have been implicated in ASD and intellectual disabilities." (PMID 40377402, 2025). "A girl with a 708 Kb microdeletion on chromosome 3q26.32 (176 221 801−176 929 584), encompassing only TBL1XR1, has an intellectual disability and brain malformation." (PMID 32449767, 2020). "It remains at present uncertain whether the abundant hypothalamic and pituitary mRNA expression of wild-type TBL1XR1 reported here is related to the intellectual disability in individuals with deletions." (PMID 26769062, 2016). "TBL1XR1, encoding for transducin β-like 1—related protein 1 (a member of HDAC containing NCOR/SMRT complexes), has been associated with different human developmental diseases, spanning from autism spectrum disorders (ASD), to West syndrome, schizophrenia (SCZ), intellectual disability." (PMID 33708771, 2021).
esophageal squamous cell carcinoma (5 papers, 2015 to 2025). Esophageal squamous cell carcinoma (ESCC) is a type of esophageal carcinoma (EC) that can affect any part of the esophagus, but is usually located in the upper or middle third. "TBL1XR1 expression has been displayed to be substantially increased in esophageal squamous cell carcinoma (ESCC) tumor tissues, which was highly associated with a more progressed ESCC disease stage and a worse patient survival, and recognized as an independent prognostic factor." (PMID 38347836, 2024). "Additionally, TBL1XR1 expression is positively correlated with disease stage in esophageal squamous cell carcinoma and promotes lymphatic metastasis in vitro and in vivo." (PMID 40074836, 2025). "Moreover, one group demonstrated that TBL1XR1 induced lymphangiogenesis and lymphatic metastasis in esophageal squamous cell carcinoma (ESCC) via the up-regulation of VEGF-C, and may represent a novel prognostic biomarker and therapeutic target for patients with ESCC." (PMID 26473853, 2015).
hepatocellular carcinoma (5 papers, 2016 to 2024). A malignant tumor that arises from hepatocytes. "We constructed the prognostic risk score for patients with hepatocellular carcinoma as follows: risk score = (0.3519) × PPM1G + (0.0637) × FKBP1A + (0.0673) × STAM + (0.0373) × MAD2L2 + (0.0031) × TBL1XR1 + (0.0172) × ANXA5." (PMID 38049741, 2023). "In hepatocellular carcinoma, through functionally inhibiting the TBL1XR1/PI3K/Akt signaling pathway, miR-1178-3p acted as a tumor suppressor." (PMID 38347836, 2024). "TBL1XR1 is typically found in the nucleus of cancer cells, but in hepatocellular carcinoma tumor cells, TBL1XR1 staining was primarily distributed in the cytoplasm." (PMID 38347836, 2024). "On the contrary, miR-1178-3p regulates the PI3K/Akt pathway by targeting TBL1XR1 to suppress hepatocellular carcinoma cell growth in vitro and inhibit xenograft tumor growth in vivo." (PMID 35813866, 2022). "In hepatocellular carcinoma, TBL1XR1 mediated the PI3K/Akt regulation by miR-1178-3p." (PMID 38347836, 2024). "By blocking the Wnt/β-catenin pathway, the stimulatory effect of TBL1XR1 on EMT of hepatocellular carcinoma may be eliminated." (PMID 38347836, 2024).
leukemia (5 papers, 2016 to 2025). A malignant (clonal) hematologic disorder, involving hematopoietic stem cells and characterized by the presence of primitive or atypical myeloid or lymphoid cells in the bone marrow and the blood. "Off-targeting activity of RAG enzymes drives the secondary mutational processes in ETV6::RUNX1 leukemia, causing SVs for example at TBL1XR1 locus, which is associated with inferior outcome." (PMID 40634509, 2025). "It is worth mentioning that secondary mutations in TBL1XR1 have recently been implicated in improving risk stratification, especially in ETV6::RUNX1 leukemia, where mutations led to inferior survival." (PMID 37469802, 2023). "The authors postulate that deletions of the following genes ETV6, VPREB1, CDKN2A/B, TBL1XR1, PAX5 as well as BTLA and CD200 are very early and essential events in leukemia development." (PMID 27933341, 2016).
lung carcinoma (5 papers, 2014 to 2024). "Lnc01578 was reported to promote lung cancer radiation resistance through decreasing miR-216b-5p expression and elevating TBL1XR1 expression." (PMID 38347836, 2024). "MiR-34c-5p may largely inhibit the malignant patterns of cancer cells by down-regulating TBL1XR1 in lung cancer." (PMID 38347836, 2024). "Moreover, TBL1XR1 expression increased in a total of five lung cancer cell lines compared with one normal bronchial epithelial cell line." (PMID 38347836, 2024). "It was determined that the miRNA expression of genes CDK19, SAMD8, TBL1XR1, and TRPS1 were significantly upregulated in the LUSC dataset between lung cancer patients and controls." (PMID 35885958, 2022).
lymphoma (5 papers, 2015 to 2022). A malignant (clonal) proliferation of B- lymphocytes or T- lymphocytes which involves the lymph nodes, bone marrow and/or extranodal sites. "In OAMZL, mutations were consistently detected in 10–20% of cases, so TBL1XR1 is one of the most frequently mutated genes in this type of lymphoma." (PMID 35267569, 2022). "Somatic mutations in the TBL1XR1 gene are mostly loss of function mutations, which usually occur in lymphoma, but rarely in AML." (PMID 36465368, 2022). "TBL1XR1 mutations have been linked to a poor prognosis in aggressive lymphomas." (PMID 35267569, 2022). "TBL1XR1 is mutated in various tumors and lymphomas, promoting tumor cell survival." (PMID 35267569, 2022). "Five genes, all with variants in two cases, were shown to be associated with lymphoma pathogenesis (ID3, PAX5, TBL1XR1, IGLL5 and APC) in previous studies." (PMID 35205758, 2022).
acute lymphoblastic leukemia (4 papers, 2012 to 2024). Leukemia with an acute onset, characterized by the presence of lymphoblasts in the bone marrow and the peripheral blood. "15% of acute lymphoblastic leukemia (ALL) patients with the ETV6-RUNX1 fusion had TBL1XR1 deletions, which made SMRT/N-CoR less effective at governing gene expression appropriately." (PMID 38347836, 2024). "Also, TBL1XR1 downregulation was found in acute lymphoblastic leukemia with positive ETV6-RUNX1 fusion." (PMID 27672238, 2016). "The TBL1XR1 mutation rate in our series and the recurrent deletions of 3q26.32 (TBL1XR1 locus) reported in PCNSL, extracerebral DLBCL, and acute lymphoblastic leukemia suggest its potential role as a tumor suppressor." (PMID 24970810, 2014).
epilepsy (4 papers, 2017 to 2025). A brain disorder characterized by episodes of abnormally increased neuronal discharge resulting in transient episodes of sensory or motor neurological dysfunction, or psychic dysfunction. "TBL1XR1 was initially added to Invitae epilepsy panels in 2016, while GeneDx added it to the test menu in 2018." (PMID 38378692, 2024).
MALT lymphoma (4 papers, 2021 to 2024). An indolent, extranodal type of non-Hodgkin lymphoma composed of small B-lymphocytes (centrocyte-like cells). "Several chromatin remodeling and transcriptional regulators are recurrently mutated in MALT lymphoma of different sites, including TBL1XR1, TET2, MLL2/KMT2D and CREBBP." (PMID 35008340, 2021). "Alternatively, TBL1XR1 and GPR34 mutations are frequent in salivary gland MALT lymphomas (24% and 19%) and uncommon in other MALT lymphomas." (PMID 38977312, 2024). "TBL1XR1 mutations are found in MALT lymphoma of the salivary gland (24%), ocular adnexa (6–18%), and in H. pylori-resistant gastric MALT lymphoma (16%)." (PMID 35008340, 2021). "Four genes recently described to be mutated in the non-pSS MALT lymphoma of the salivary gland, TBL1XR1, CCR6, TNFAIP3 and NOTCH2, were also mutated in a subset of our pSS-MALT lymphomas." (PMID 35205758, 2022).
nasopharyngeal carcinoma (4 papers, 2014 to 2024). A carcinoma arising from the nasopharyngeal epithelium. "We detected the expression of TBL1XR1 protein and mRNA in nasopharyngeal carcinoma (NPC) cell lines and biopsies by western blotting, real-time PCR and immunohistochemical staining (IHC)." (PMID 25145705, 2014). "Furthermore, TBL1XR1 activated NF-κB as to suppress cisplatin-induced apoptosis of nasopharyngeal cancer cells." (PMID 27672238, 2016). "Additionally, TBL1XR1 expression was found to be raised in nasopharyngeal carcinoma (NPC) cell lines, detectable in 89.52% tumor tissues, and highly expressed in 49.52% of the NPC tumor tissues." (PMID 38347836, 2024).
osteosarcoma (4 papers, 2022 to 2024). A usually aggressive malignant bone-forming mesenchymal neoplasm, predominantly affecting adolescents and young adults. "Another study also demonstrated the upregulation of TBL1XR1 in osteosarcoma tumor tissues and TBL1XR1 expression was positively linked to present metastasis and advanced Enneking stage." (PMID 38347836, 2024). "Finally, in human osteosarcoma samples, TBL1XR1 protein levels strongly associated with mRNA expression levels of the stemness markers." (PMID 38347836, 2024). "In osteosarcoma, TBL1XR1 expression was primarily found in the nucleus and only rarely in the cytoplasm." (PMID 38347836, 2024). "Meanwhile, osteosarcoma cells with overexpressed TBL1XR1 had higher expression of stemness markers including ABCG2, BMI1, SOX2, NANOG, and OCT4, indicating that TBL1XR1 endowed osteosarcoma cells with stem cell-like properties." (PMID 38347836, 2024). "In osteosarcoma cells, by specifically targeting TBL1XR1, miR-186-5p was downregulated and prevented cell proliferation, migration, and cell invasion." (PMID 38347836, 2024). "More importantly, the influence of TBL1XR1 on tumor development of osteosarcoma were mediated by stimulation of the STAT3 signaling pathway." (PMID 38347836, 2024). "TBL1XR1 thus provides osteosarcoma cells with tumorigenic properties and promotes the recurrence of osteosarcoma in a STAT-3 signaling dependent manner." (PMID 35582537, 2022). "The results of the two investigations suggested that TBL1XR1 may be crucial for the growth of osteosarcoma." (PMID 38347836, 2024). "Additionally, TBL1XR1 expression was identified as an independent prognostic factor for osteosarcoma patients." (PMID 38347836, 2024). "Likewise, comparatively to the normal human osteoplastic cell line, TBL1XR1 levels was elevated among all osteosarcoma cell lines both at the protein and mRNA levels." (PMID 38347836, 2024). "Moreover, miR-186-5p repressed osteosarcoma migration or invasion through regulating TBL1XR1 expression." (PMID 36059626, 2022). "TBL1XR1 is a transcriptional co-factor which is overexpressed in osteosarcoma patients." (PMID 35582537, 2022). "Osteosarcoma samples had significantly higher levels of TBL1XR1 expression than the paired adjacent non-tumor tissues." (PMID 38347836, 2024). "TBL1XR1’s cytoplasmic staining did not notably correlate with clinicopathologic factors or disease prognosis of osteosarcoma patients." (PMID 38347836, 2024).
autism (3 papers, 2016 to 2025). Persistent deficits in social interaction and communication and interaction as well as a markedly restricted repertoire of activity and interest as well as repetitive patterns of behavior. "We found differential expression of autism-relevant genes in our DE gene list that are also associated with cell adhesion (Dscam, Reln) or gene regulation (Kat2b, Kmt2c, Med13/Med13l, Tbl1xr1, Ubn2)." (PMID 33757588, 2021). "This contrasts with loss-of-function germline TBL1XR1 deletions and other TBL1XR1 mutations that have been implicated in autism." (PMID 26769062, 2016).
colorectal cancer (3 papers, 2016 to 2024). A primary or metastatic malignant neoplasm that affects the colon or rectum. "TBL1XR1 was found to have prominent expression levels in the nuclear of tumor cells in 57.4% of colorectal cancer (CRC) tissues and in 72.3% of liver metastases." (PMID 38347836, 2024). "In colorectal cancer, TBL1XR1 also mediated the modulation of VEGF-C, thus mediating the process of lymph node metastasis." (PMID 38347836, 2024).
diffuse large B-cell lymphoma (3 papers, 2015 to 2024). "The newly identified TBL1XR1/TP63 gene fusion was discovered using transcriptome sequencing in diffuse large B-cell lymphoma (DLBCL)." (PMID 38347836, 2024).
lung squamous cell carcinoma (3 papers, 2014 to 2022). "TBL1XR1 is up-regulated in a variety of solid tumors, including lung squamous cell carcinoma and is related to tumor stage and metastasis." (PMID 35475502, 2022). "For lung squamous cell carcinoma, TBL1XR1 up-regulation generates a mesenchymal phenotype while TBL1XR1 down-regulation produces an epithelial phenotype." (PMID 35475502, 2022).
primary central nervous system lymphoma (3 papers, 2024). A non-Hodgkin or Hodgkin lymphoma that arises in the brain or spinal cord as a primary lesion. "TBL1XR1 somatic mutations were found in 14% of primary central nervous system lymphoma (PCNSL) cases." (PMID 38347836, 2024). "Lastly, primary central nervous system lymphoma (PCNSL) is an aggressive large B-cell lymphoma that also displays CDKN2A loss and mutations in MYD88, CD79B, and TBL1XR1, thus with potentially definable genetic subtypes." (PMID 40191738, 2024).
Rett syndrome (3 papers, 2018 to 2024). A severe neurodevelopmental disorder affecting the central nervous system. "Indeed, a recent crystal structure of the NID bound to the TBL1XR1 subunit, which is shared by NCoR1/2 complexes, showed that four adjacent amino acids that are individually mutated in Rett syndrome (one of which is R306) all make intimate molecular contacts with the WD40 domain of TBL1XR1." (PMID 30463906, 2018). "Nearly one-third of subjects with TBL1XR1-related disorder in the current survey reported seizures, a lower prevalence than is seen in Angelman Syndrome and Rett Syndrome, but similar to related disorders such as Phelan-McDermid syndrome." (PMID 38378692, 2024).